MIR3193 (microRNA 3193)
Synonyms: hsa-mir-3193
Gene: MicroRNA gene on chromosome 20 (31,607,186 to 31,607,240, forward strand). Ensembl gene ENSG00000264395.
Diseases named in the same sentence as MIR3193 in open-access papers:
MIR3193 is named in the same sentence as 4 diseases in open-access papers, as found by Europe PMC text mining. Sharing a sentence is not in itself a finding about the gene and the disease. The quoted sentences say what the papers report.
breast tumours (1 paper, 2022). "MTND6P4 and MIR3193 are frequrently methylated in primary breast tumours tumurs (9/19, 16/19)." (PMID 35058523, 2022).
tumour (1 paper, 2022). "Of these, the promoter regions of three genes (MIR124-2, RP11-713P17.4, and NUS1P3) were hypermethylated in BBM and three genes (MIR3193, CTD-2023M8.1 and MTND6P4) were hypomethylated in BBM relative to the primary tumours." (PMID 35058523, 2022).
MIR3193 also shares sentences with these, for which no sentence is quoted: cancer (1 paper); glioma (1).